TNF (tumor necrosis factor)
Diseases named in the same sentence as TNF in open-access papers (continued):
Sharing a sentence is not in itself a finding about the gene and the disease.
autoimmune disease (continued). "Drugs that block the effect of TNF-α have shown beyond dispute role in modulating the activity of many autoimmune diseases." (PMID 27840642, 2016). "Certolizumab is derived from an antibody fragment that recognizes tumor necrosis factor α (TNFα), which is partly responsible for the inflammatory effect for several autoimmune disorders." (PMID 26516849, 2015). "The importance of TNF-α in the control of latent or persistent mycobacteria has been revealed by the high risk of reactivation TB observed in patients undergoing anti-TNF-therapy for autoimmune diseases." (PMID 25999670, 2015). "The genetic associations between IL-10, TNF/LTA, and CTLA-4 polymorphisms have been investigated extensively in many autoimmune diseases and malignancies, and have been confirmed for certain diseases." (PMID 26108796, 2015). "Interleukin-10 (IL-10) and tumor necrosis factor (TNF) are key cytokines that have been intensively investigated in autoimmune diseases and malignancies." (PMID 26108796, 2015). "Using our system-level model, we previously simulated ADA production induced by adalimumab, a fully anti-TNF alpha IgG1 mAb used to treat various inflammatory and autoimmune diseases, with a danger signal of 350 ng LPS." (PMID 26682236, 2015). "The therapeutic antagonism of cytokines such as TNF-α or IL-1 by biological agents has been indicated to be a successful strategy in certain autoimmune diseases." (PMID 25821355, 2015). "TNF-α treatment prevents some autoimmune diseases including T1DM because autoreactive T cells were more susceptible to TNF-α-induced apoptosis than healthy T cells." (PMID 26039731, 2015). "TNFR2 agonists and TNF-inducers have recently emerged as potentially new treatment strategies for specific and select autoimmune diseases such as multiple sclerosis and type-1 diabetes." (PMID 26266038, 2015). "TNF-α antagonists are currently used to treat patients with various autoimmune diseases in gastroenterology, rheumatology and dermatology." (PMID 26474294, 2015). "Unwanted TNFα can be responsible for debilitating disease, as seen in allergies and autoimmune diseases that respond strongly to anti-TNFα therapies." (PMID 25948885, 2015). "We report here an association of increased expression of ICAM-1 on monocytes with a less favorable response to TNF inhibition, which would imply them in the perpetuation of the autoimmune disease." (PMID 26251236, 2015). "Blocking of TNF signaling has therefore been evaluated in various inflammatory diseases and is successfully used for treatment of autoimmune diseases such as rheumatoid arthritis, Crohn's disease, and psoriasis." (PMID 25834699, 2015). "During the past decade, highly potent biological agents targeting TNF-α, IL-6 and p40 to enhance or replace conventional immunosuppressive therapies have made significant advances in the treatment of autoimmune diseases." (PMID 26384304, 2015). "IL-17, which can be secreted by Th17 cells, was treated as a therapeutic target in some autoimmune disease, which promote secretion of multiple inflammation factors like TNF-α, IL-1, IL-6 and IL-8." (PMID 26677348, 2015). "Th17 cells are characterized by the production of various proinflammatory cytokines including IL-6, IL-17, IL-21, and TNF-α, and play crucial roles in the pathogenesis of various autoimmune diseases, including RA." (PMID 26544846, 2015). "For example, transgenic mice expressing a mutant TNF that cannot be cleaved, thus preventing the formation of sTNF, are largely protected against the induction of autoimmune diseases." (PMID 25834699, 2015). "Pro-inflammatory cytokines, for example, TNFα, IL-18, IL-12 and IL-23, released from M1-like macrophages have been identified as important mediators in several autoimmune diseases." (PMID 25889583, 2015). "Various defects in TNF signaling pathways occur in both human and mouse models of several autoimmune disorders." (PMID 26266038, 2015).
autoimmune disease (continued). "T cell-dependent ADA production is thought to be the major pathway through which TPP induce immunogenicity as in the case of IgG1 and IgG4 generated against anti-TNFα mAb to treat a variety of inflammatory and autoimmune diseases." (PMID 26682236, 2015). "sTNF, TNF inducers or TNFR2 agonism have shown promise for treating these subtypes of autoimmune diseases." (PMID 26266038, 2015). "The progranulin (PGRN) is known to protect regulatory T cells (Tregs) from a negative regulation by TNF-α, and its levels are elevated in various kinds of autoimmune diseases." (PMID 25393765, 2014). "The introduction of anti-TNFα drugs into the treatment of RP, ankylosing spondylitis, and other autoimmune diseases has revolutionized the management of patients with active diseases that resist conventional therapy." (PMID 25276463, 2014). "Tumour necrosis factor (TNF) is a proinflammatory cytokine that is known to regulate inflammation in a number of autoimmune diseases, including multiple sclerosis (MS)." (PMID 24587232, 2014). "The present meta-analysis provided consistent evidence that marine-derived n-3 PUFAs supplementation had a significant lowering effect on fasting blood levels of CRP, IL-6 and TNF-α in subjects with chronic non-autoimmune disease and healthy subjects." (PMID 24505395, 2014). "Accordingly, blockade of TNF in patients with chronic inflammation and autoimmune diseases is currently being used therapeutically." (PMID 25400932, 2014). "Under normal physiological conditions, the basal level of TNF-alpha remains low, but TNF-alpha concentration increases in acute inflammation, trauma and autoimmune diseases." (PMID 24852285, 2014). "This promising strategy has not been used so far for IL-6 but has been successfully established for other cytokines, including tumor necrosis factor-alpha (TNFα) and IL-1β and IL-23 in different autoimmune diseases." (PMID 25059342, 2014). "TNF-α is mainly involved in the perpetuation of the inflammatory cascades in autoimmune diseases, which affect connective tissues where the connective tissues become hypercontracted due to inflammation." (PMID 25276195, 2014). "Restricted cubic spline analysis and subgroup analysis showed that the lowering effect of marine-derived n-3 PUFAs on CRP, IL-6 and TNF-α in subjects with chronic non-autoimmune disease became weakened when body mass index was greater than 30 kg/m2." (PMID 24505395, 2014). "There is evidence that a small percentage of patients using anti-TNFα therapy will develop autoimmune diseases including vasculitis, lupus-like syndrome, and cutaneous psoriatic lesions." (PMID 25276463, 2014). "MIF is a pro-inflammatory mediator and an upstream regulator of expression of many cytokines, including IL-1b, IL-8, IFN-ɤ, TNF-α, and IL-6 in autoimmune diseases." (PMID 25506398, 2014). "Increased serum values of TNF-α have been detected in autoimmune disease and many malignancies including lymphomas." (PMID 24857911, 2014). "Although the effect of TNF-α on Tregs function remains controversy, the beneficial and therapeutic effects of Tregs in autoimmune diseases have been well-accepted by the scientific community." (PMID 25393765, 2014). "An overlapping feature across autoimmune disorders is various defects in TNF signaling through its two receptors." (PMID 24391650, 2013). "In brief, a role for TNF has been suggested in autoimmune diseases, such as psoriasis, inflammatory bowel disease, arthritis, systemic sclerosis, diabetes mellitus and multiple sclerosis." (PMID 23852022, 2013). "Nuclear factor-kB is thwarted from entering the nucleus to transcribe pro-survival genes in autoimmune diseases featuring defects in TNF signaling." (PMID 24391650, 2013). "Tumor necrosis factor (TNF) is a pleiotropic cytokine most known for pro-inflammatory (Th1) functions in multiple autoimmune diseases." (PMID 23717310, 2013).
autoimmune disease (continued). "One new treatment strategy for autoimmune disease is selective destruction of autoreactive T cells by administration of TNF, TNF inducers, or TNFR2 agonism." (PMID 24391650, 2013). "As polyethylene glycol does not cross the placenta, this drug can be administrated to pregnant women who have autoimmune diseases and are in need of anti-TNF-alpha therapy." (PMID 24453421, 2013). "TNF plays a central role in the so-called “cytokine storm” characteristic of several autoimmune diseases." (PMID 24312346, 2013). "Adalimumab is a fully human subcutaneously administered IgG anti-TNF antibody that binds to TNFα, preventing it from activating TNF receptors, thus downregulating the inflammatory reactions associated with several autoimmune diseases." (PMID 24191219, 2013). "Inhibitors of TNFα are already in clinical use for other indications (autoimmune diseases), and our findings suggest that they should be combined with antihormonal approaches and modalities targeting the EGF-HER2 pathway." (PMID 24369447, 2013). "Individuals with immune-mediated inflammatory disorders (IMID) are also known to be at increased risk of developing active TB, particularly after the use of tumour necrosis factor (TNF)—alpha inhibitors to treat a variety of autoimmune disease." (PMID 23476764, 2013). "Since type I IFN and BAFF seem to be involved in the pathogenesis of SS as well as of other autoimmune diseases, anti-TNFα agents should be avoided in patients with autoimmune diseases, including SS." (PMID 23556533, 2013). "Blockage of TNF-α is already used as standard treatment in various autoimmune diseases, whereas clinical trials to evaluate blockage of IL-6 and IL-1β in inflammatory diseases and cancer are ongoing." (PMID 23616009, 2013). "Anti-tumour necrosis factor (anti-TNF) therapies are an important recent development in the treatment of autoimmune disease." (PMID 23663548, 2013). "One such system that generated immense attention owing to its central role in inflammatory effect, immunological response, but also in several autoimmune diseases and several pathogeneses is the tumor necrosis factor (TNF)." (PMID 22568977, 2012). "Surprisingly, such specific regimens are not in place at present, still relying on a few trials with B-cell-targeted and TNF-directed therapies evolved from testing on other autoimmune diseases." (PMID 23116360, 2012). "An effective blockade of TNFα-dependent cytokine cascades and leukocyte recruitment as well as good clinical and serological response rates have led to the establishment of therapy with TNFα inhibitors in RA and other autoimmune disorders." (PMID 23079185, 2012). "While TNF-α contributes to the inflammatory process, IL-10 has an important role in modulating the inflammatory response and autoimmune disease." (PMID 22454760, 2012). "Mast cells are immune cells critical in the pathogenesis of allergic, but also inflammatory and autoimmune diseases through release of many pro-inflammatory cytokines such as IL-8 and TNF." (PMID 22470478, 2012). "It is a known fact that disruption of TNF signaling pathway occurs in a number of autoimmune diseases, including MS." (PMID 23202976, 2012). "For example, the HLA class III region contains clusters of genes such as TNF-α, HSP70, C4A/C4B, and NF-κBIL1 that are seminal in cellular function and are also associated with numerous autoimmune diseases." (PMID 22928105, 2012). "Tumor Necrosis Factor (TNF)-α, is a paracrine inhibitor of melanocytes, which plays a critical role in the pathogenesis of several autoimmune diseases including vitiligo, as abnormal immune responses have frequently been observed in vitiligo patients." (PMID 23284977, 2012). "In the current study, BCG was expressly chosen as a treatment for its induction of TNF, which has been shown to play a therapeutic role in at least in four rodent models of five autoimmune diseases and in vitro." (PMID 22905105, 2012).
autoimmune disease (continued). "Several studies in mice have shown that TNF is essential to control infection and in humans the treatment of autoimmune disease with a TNF blocking antibody results in the activation of latent TB infection." (PMID 22844476, 2012). "Physicians using tumor necrosis factor-alpha inhibitors in the treatment of various rheumatic and other autoimmune diseases should be aware of the potential for the development of glycemic disturbance in these patients." (PMID 22234148, 2012). "Some investigators advocate therapy with TNF-α or TNF-α inducers as treatments for autoimmune diseases including T1D." (PMID 22606220, 2012). "In clinic, blockade of TNF-α by anti-TNF-α antibodies notably reduces inflammation and ameliorates clinical outcomes, suggesting that cytokines play a central role in autoimmune diseases." (PMID 22069489, 2011). "TNF-α has been proved to have certain effects on autoimmune processes and has become a key therapeutic target for many autoimmune diseases." (PMID 21305012, 2011). "For example in the autoimmune diseases juvenile idiopathic arthritis and Sjogren's syndrome, treatment with anti-TNF-α therapy increased IFN-α signaling in peripheral blood." (PMID 22195005, 2011). "Therapies directed at both of these cytokines are either already in use (TNF-α) or in clinical trials (type I IFN) in autoimmune disease." (PMID 22195005, 2011). "NFκB regulates the production of MCP-1 (which is stimulated by TNF-α and IL-6) and is known to be a key payer in the immune response, cancer, inflammatory and autoimmune diseases." (PMID 20824139, 2010). "The failure of Etanercept in some RA patients and in some autoimmune diseases, such as Crohn's disease, was likely due to its low affinity to TNFα." (PMID 20140191, 2010). "In summary, both infliximab and adalimumab are effective in autoimmune diseases but their role in SLE is still pending in view of the dual functions of TNF in inflammation and immune regulation." (PMID 27713252, 2010). "Tumor Necrosis Factor alpha (TNF-α) is a pleiotropic cytokine which plays a primary role in the induction of inflammation in autoimmune diseases." (PMID 21180427, 2010). "TNF-α has also shown to be protective as shown by the increased incidence of TB in patients given anti-TNF treatments for autoimmune diseases." (PMID 20574540, 2010). "Definitely, the role of TNF-α in the pathogenesis of alopecia areata as well as other autoimmune diseases has to be further investigated as far as treatment with antiTNF-α agents is considered." (PMID 20300578, 2010). "Our results emphasize the balance between IFNα and TNFα in RA, and provide mechanistic insights into the possible roles of DC subsets in mediating the shift in autoimmune disease manifestations by therapeutics that inhibit TNFα." (PMID 19563672, 2009). "Although not tested in this study, previous studies have demonstrated the efficacy of human TNFR1 on inhibiting rodent TNF-α in animal models of autoimmune diseases." (PMID 20003451, 2009). "Treatment of autoimmune diseases with TNF-α antagonists results in reactivation of Mtb and development of clinical disease in these individuals." (PMID 19636364, 2009). "In humans, beneficial effects of anti-TNF-α treatments in patients with autoimmune diseases are proved; though surprisingly a side effect of this treatment is the induction or exacerbation of humoral autoimmunity disorders." (PMID 19490629, 2009). "sTNFRII is an important counter-regulatory cytokine for TNF-α as made evident by the marked therapeutic effects of exogenous sTNFRII in the treatment of certain autoimmune diseases." (PMID 19025588, 2008). "The cytokine tumor necrosis factor (TNF)-α is produced by macrophages and dendritic cells as a primary response to infections and tissue damage, and is constitutively expressed in several autoimmune diseases." (PMID 18796140, 2008).
autoimmune disease (continued). "TNFA, the gene encoding the pro-inflammatory cytokine TNF-α has been the focus of several association studies of autoimmune diseases." (PMID 18644131, 2008). "IL-13, a prototype Th2 cytokine, is a major inducer of fibrosis in many chronic infectious and autoimmune diseases, while TNF has been shown to be a critical component of the IL-13 mediated protective Th2 response during helminth infection." (PMID 17205112, 2006). "Several studies have analyzed the association of IL-10 or TNFα genetic variants with susceptibility to and outcome of SLE and other autoimmune diseases, showing variable results in most cases." (PMID 16507146, 2006). "Similarly, the occurrence of TB after anti-TNF-α therapy for autoimmune disease confirmed the importance of TNF-α in control of latent infection." (PMID 41499279, 2026). "TNF-α blockade is a successful treatment for several autoimmune diseases." (PMID 41142785, 2025). "Observational data suggest that patients with autoimmune disease on anti-TNF agents might even experience a slight increase in cerebrovascular events, possibly due to impaired vascular repair mechanisms or thrombogenic side effects." (PMID 40869247, 2025). "Consequently, TNF‐α inhibitors, as primary biologics for managing autoimmune diseases, are naturally anticipated to be effective in treating AA." (PMID 40260013, 2025). "Here, we computationally identified three peptides (OB5, OB6, and OB8) that likely modulate the TNF signaling pathway and could have therapeutic value for tissue regeneration, wound healing, and treatment of autoimmune diseases." (PMID 40338229, 2025). "In addition, as an autoimmune disease, vitiligo involves complex interactions of multiple cytokines like interferons, tumor necrosis factor, and chemokines." (PMID 40725033, 2025). "These cells are enriched in autoimmune diseases, such as IgG4-related disease, where they promote inflammation through the production and secretion of autoantibodies and pro-inflammatory cytokines, including TNF-α and IFN-γ." (PMID 41472742, 2025). "TNF-α serves as a potent regulator of inflammation and autoimmune diseases." (PMID 39826048, 2025). "Tumor necrosis factor inhibitors (TNFi) are often used in the treatment of autoimmune diseases." (PMID 41420219, 2025). "As TNF-α is a known key player in several autoimmune diseases and regulator of CNS functional homeostasis in healthy state, altered levels of TNF-α from astroglial EVs may have a harmful effect in HCWs with severe psychological distress." (PMID 40917429, 2025). "Similarly, TNF-α inhibitors, which are widely used in autoimmune diseases, are being investigated for their potential to reduce inflammation-driven tumor progression in cancer." (PMID 40563999, 2025). "As blocking TNF-α can lead to increased IL-17 production, which is counterproductive in several IL-17-driven autoimmune diseases (such as HS and VHK or VKHLD as described here), disease exacerbations or new autoimmune diseases during TNF-α blocker therapy should be carefully monitored." (PMID 41142785, 2025). "Therefore, TNF inhibitors (TNFi) are widely utilized for the treatment of various autoimmune diseases." (PMID 41346622, 2025). "Thalidomide and its analogues can inhibit the synthesis of TNF-α by activated monocytes and have demonstrated efficacy in autoimmune diseases such as RA, SLE, and systemic sclerosis, although the precise mechanisms were previously unknown." (PMID 40040717, 2025). "Both IL-17 and TNF are pivotal in autoimmune diseases like JIA and ankylosing spondylitis." (PMID 40406113, 2025). "TNF-α plays a key role in acute inflammation and autoimmune diseases, IFN-γ amplifies cell-mediated immunity by stimulating macrophages and natural killer cells, and IL-2 is central to immune regulation and homeostasis and is synthesized primarily by activated T cells." (PMID 41459048, 2025).